TNFRSF14 (TNF receptor superfamily member 14)
Diseases named in the same sentence as TNFRSF14 in open-access papers (continued):
Sharing a sentence is not in itself a finding about the gene and the disease.
colitis (8 papers, 2011 to 2025). Inflammation of the colon. "Studies have shown that TNFRSF14 expression by innate immune cells has an important role in preventing intestinal inflammation in a T cell transfer model of colitis." (PMID 39144148, 2024). "In a Tnfsf14(-/-) mouse model, it was observed that these mice developed more severe colitis compared to control mice, indicating the protective role of TNFRSF14 in colitis." (PMID 39144148, 2024).
viral infection (8 papers, 2012 to 2025). "The TNF receptor superfamily member herpesvirus entry mediator (HVEM) (TNFRSF14) was initially identified as a receptor for viral infection." (PMID 39979981, 2025). "We also show that IL22 reduces the expression of viral entry receptors (e.g. ACE2, TMPRSS2, DPP4, CD46 and TNFRSF14), increases the expression of anti-viral proteins (e.g. RSAD2, AOS, ISG20 and Mx1) and, consequently, reduces the viral infection of neighboring cells." (PMID 34045640, 2021).
gastric cancer (7 papers, 2020 to 2025). A primary or metastatic malignant neoplasm involving the stomach. "High VISTA expression was independently correlated with high BTLA, TIM-3, and TNFRSF14, and with a diagnosis of pancreatic, small intestine, and stomach cancer." (PMID 38503143, 2024). "There is a relationship between CNN1 and tumor-infiltrating lymphocytes (TILs), and the marker genes NRP1 and TNFRSF14 of TILs are significantly related to CNN1 expression in gastric cancers." (PMID 37153789, 2023). "In gastric cancer, DNMT3B promotes tumor progression by methylating the MYH11 gene, thereby decreasing its expression and allowing the increase of TNFRSF14, which supports cancer development." (PMID 39185313, 2024).
lung cancer (7 papers, 2021 to 2026). A malignant neoplasm involving the lung. "The TNFRSF14 of breast and lung cancer is most expressed in macrophages, while in colorectal cancer the highest expression is in endothelial, epithelial, and fibroblasts, and macrophages are only moderately expressed." (PMID 39120585, 2024).
ovarian carcinoma (7 papers, 2020 to 2025). A malignant neoplasm originating from the surface ovarian epithelium. "In ovarian cancer, the overexpression of HVEM (TNFRSF14), a member of the TNF receptor superfamily, is associated with the activation of AKT/mTOR signaling, promoting the expression of Bcl-2 and HIF-1α, which is positively associated with tumor proliferation and negatively related to cell apoptosis." (PMID 36358792, 2022). "The relationship between the ratio of TNFRSF14/ACTB mRNA expression and clinicopathological parameters in ovarian cancer tissues." (PMID 40105652, 2025). "MSLN was positively correlated with immunosuppressive genes in ovarian cancer, such as LGALS9, CD276, TMIGD2, CD200, TNFRSF14, and human leukocyte antigen (HLA)-related families including HLA-DRA, HLA-DRB1, HLA-DPA1, HLA-DMA, HLA-E, etc.." (PMID 35692779, 2022).
B cell lymphomas (6 papers, 2019 to 2025). "Remarkably, CD274 mutations and deletions are significantly associated with a loss of function mutations of TNFRSF14 in this low grade B-cell lymphoma, which typically arises from a background of autoimmune Hashimoto’s thyroiditis." (PMID 34021249, 2021). "Mutational profiling using a custom panel of 168 genes associated with aggressive B-cell lymphomas confirmed mutations in ACTB, ARID1B, DUSP2, DTX1, HLA-B, PTEN, and TNFRSF14." (PMID 36975733, 2023). "The HVEM(TNFRSF14):LIGHT/BTLA/CD160 axis is another relevant immune modulatory pathway in B-cell lymphoma." (PMID 35071240, 2021). "MYD88 mutations did not co-occur with EZH2 or TNFRSF14 mutations, which are mostly found in B-cell lymphomas of the germinal center as opposed to the activated B-cell lymphomas, in which MYD88 is commonly mutated." (PMID 40511879, 2025).
glioblastoma (6 papers, 2019 to 2025). The most malignant astrocytic tumor (WHO grade IV). "Based on these findings, we established a risk signature comprised of CD276, TNFRSF14, TNFSF14, TNFSF4, CD40, and TNFRSF18 to predict OS and response to immune checkpoint blockade in glioblastoma patients." (PMID 38365809, 2024). "In our model, the genes TNFRSF14 and TNFSF14 are also associated with a poorer prognosis in glioblastoma through complex interaction networks." (PMID 38365809, 2024). "Similar associations were observed in the CGGA-glioblastoma cohort for CD40, CD276, TNFRSF14, and TNFSF14, except for TNFSF4 and TNFRSF18." (PMID 38365809, 2024). "The evidence presented suggests a potential correlation between TNFRSF14 and TNFSF14 with poorer prognosis in glioblastoma." (PMID 38365809, 2024). "In addition, we obtained representative IHC staining images of CD276, TNFSF4, TNFRSF14, CD40, TNFSF14, and TNFRSF18 in both normal tissues and glioblastoma samples from the Human Proteome Atlas." (PMID 38365809, 2024).
rheumatoid arthritis (6 papers, 2013 to 2025). A chronic, systemic autoimmune disorder characterized by inflammation in the synovial membranes and articular surfaces. "The other two—LAIR1 and TNFRSF14—appear to be more specifically associated with rheumatoid arthritis." (PMID 39887658, 2025). "TNFRSF14 has been linked to Crohn disease and rheumatoid arthritis; it is also reported to be a herpesvirus entry mediator." (PMID 32951330, 2020). "For five of the 16 putative core genes—CD5, CTLA4, SLAMF1, PDCD1, and TNFRSF14—that were identified through association of GATE scores with rheumatoid arthritis, associations of rheumatoid arthritis with SNPs within 200 kb of the transcription site are listed in the GWAS catalog." (PMID 39887658, 2025).
multiple myeloma (5 papers, 2016 to 2025). "However, CD160 and TNFRSF14 are highly expressed in a variety of tumors (e.g. chronic lymphocytic leukemia and multiple myeloma) and promote tumor evasion of immune surveillance by regulating NK and T cell activity." (PMID 40342824, 2025).
lupus (4 papers, 2021 to 2025). "TWEAK, the ligand of TNFRSF12A, has previously been reported to be involved in lupus pathology, and LIGHT (TNFSF14), a ligand of HVEM (TNFRSF14), is commonly dysregulated in murine lupus." (PMID 39688922, 2024). "Transcriptional activation of TNF signaling in lupus Th cells correlated with plasma levels of TNF family cytokines, including TWEAK, and with protein dysregulation of TNF family receptors, including HVEM (herpes virus entry mediator: TNFRSF14)." (PMID 39688922, 2024). "Other TNF family receptors, including TNFRSF12A (TWEAKR) and TNFRSF14 (HVEM), showed heterogeneous expression patterns but were not significantly altered between lupus groups." (PMID 39688922, 2024).
pancreatic cancer (4 papers, 2020 to 2025). "Differential expression and pathological stage analyses revealed that in comparison to the normal pancreas tissue, the expression levels of CD112 and TNFRSF14 were not significantly deregulated in the pancreatic tumors, and did not regularly fluctuate between each of the two different stages." (PMID 32508042, 2020). "Furthermore, the survival analyses of patients with pancreatic cancer clearly indicated that the expression levels of CD112 and TNFRSF14 had no significant influence on overall survival (OS) and disease‐free survival (DFS, also called relapse‐free survival [RFS])." (PMID 32508042, 2020).
prostate carcinoma (4 papers, 2021 to 2025). A carcinoma that arises from epithelial cells of the prostate gland. "Additionally, our analysis indicated that G_Anaerofilum may decrease the risk of prostate cancer via TNFRSF14 pathway." (PMID 39882449, 2024). "Among the genes of interest identified, TNFRSF14 underexpression in both Black-derived prostate cancer cell lines represents a particularly intriguing finding warranting further investigation." (PMID 41038711, 2025). "RNA sequencing analysis revealed consistent underexpression of TNF family genes, particularly TNFRSF14, in prostate cancer cells from Black donors correlating with differential drug responses." (PMID 41038711, 2025). "Notably, G_Ruminococcaceae UCG014/TNFSF10 axis and G_Anaerofilum/TNFRSF14 axis were found to act as protective factors, while the other two signaling axes played a crucial role in promoting the progression of prostate cancer." (PMID 39882449, 2024). "G_Anaerofilum/TNFRSF14 axis might serve as a promising target for immunotherapy in prostate cancer." (PMID 39882449, 2024). "The consistent underexpression of TNFRSF14 and other TNF family genes in Black-derived prostate cancer cell lines highlights potential molecular mechanisms underlying these differential responses." (PMID 41038711, 2025). "Further MR analyses of these positive results indicated that G_Ruminococcaceae UCG014/TNFSF10 axis, G_Anaerofilum/TNFRSF14 axis, G_Erysipelotrichaceae UCG003/TNFSF10 axis, and P_Proteobacteria/cholesterol axis were key signaling pathways involved in the progression of prostate cancer." (PMID 39882449, 2024).
asthma (3 papers, 2016 to 2025). "To define the importance of MC expression of TNFRSF14 in vivo, we induced our model of asthma in genetically MC-deficient KitW-sh/W-sh mice engrafted intravenously (i.v.)with Tnfrsf14+/+ or Tnfrsf14−/− BMCMCs." (PMID 27982078, 2016). "We considered the possibility that the abnormalities in the pathology of the asthma models which we observed in mice genetically deficient in TNFRSF14 might reflect effects of TNFRSF14 on the sensitization and/or effector phases of TH2 responses." (PMID 27982078, 2016). "TNFRSF14 expression by MCs also can exacerbate several features of the pathology in two different mouse models of Ag-induced asthma in vivo." (PMID 27982078, 2016). "Taken together, these findings strongly suggest that TNFRSF14:TNFSF14 interactions can influence the pathology of asthma models by mechanisms in addition to effects on the production of Ag-specific IgE." (PMID 27982078, 2016). "Our data indicate that the features of these asthma models that were significantly influenced by TNFRSF14 include blood levels of Ag-specific IgE, airway inflammation, AHR, lung collagen content and airway goblet cell hyperplasia and BAL Muc5AC content." (PMID 27982078, 2016). "Here the authors show that TNFSF14 acting on its receptor TNFRSF14 on mast cells enhances their IgE-dependent activation and that interference with this pathway attenuates features of asthma pathology in mice." (PMID 27982078, 2016). "An analysis of gene expression patterns in nasal lavage specimens from children with asthma found that TNFRSF14 was one of the genes exhibiting higher expression during picorna virus-induced asthma exacerbations compared with values in specimens obtained 7–14 days after the infection." (PMID 27982078, 2016). "To evaluate whether the data obtained in our OVA model could be confirmed in a second model of asthma, we sensitized Tnfrsf14+/+or Tnfrsf14−/− mice i.n. with HDM from Dermatophagoides pteronyssinus and challenged them i.n. weekly for 10 weeks with HDM." (PMID 27982078, 2016). "We then assessed whether expression of TNFRSF14 solely on MCs is sufficient to enhance the features of this asthma model." (PMID 27982078, 2016). "In mouse models of asthma, TNFRSF14 blockade with a neutralizing antibody administered after antigen sensitization, or genetic deletion of Tnfrsf14, diminishes plasma levels of antigen-specific IgG1 and IgE antibodies, airway hyperreactivity, airway inflammation and airway remodelling." (PMID 27982078, 2016). "Recently, the co-receptor, HVEM (herpesvirus entry mediator), also known as tumor necrosis factor receptor superfamily 14 (TNFRSF14), has emerged as a potential novel biomarker for asthma, thanks to its reported association with disease severity in asthma patients." (PMID 40226621, 2025). "Moreover, in WT mice, blocking TNFRSF14:TNFSF14 interactions with an antibody administered weeks after Ag sensitization can diminish multiple features of asthma pathology, including blood levels of Ag-specific IgE, airway inflammation and AHR, and airway remodelling." (PMID 27982078, 2016). "The TNF superfamily member TNFSF14 (LIGHT), via interactions with the receptor TNFRSF14 (HVEM), can support TH2 cell generation and longevity and promote airway remodelling in mouse models of asthma, but the mechanisms by which TNFSF14 functions in this setting are incompletely understood." (PMID 27982078, 2016). "This possible involvement of TNFRSF14 (whether on MCs or other cell types) in features of asthma inflammation and remodelling has not before been specifically investigated." (PMID 27982078, 2016). "By studying the phenotype of our asthma models in mice that did or did not express TNFRSF14, and that did or did not contain MCs that expressed TNFRSF14, we avoided problems associated with drawing conclusions from in vitro, histological or IHC analyses taken in isolation." (PMID 27982078, 2016).
asthma (continued). "Finally, by analysing two types of genetically MC-deficient mice after engrafting MCs that either do or do not express TNFRSF14, we show that TNFRSF14 expression on MCs significantly contributes to the development of multiple features of asthma pathology." (PMID 27982078, 2016).
atherosclerosis (3 papers, 2022 to 2024). A disease characterized by the build-up of fatty material and calcium deposition in the arterial wall resulting in partial or complete occlusion of the arterial lumen. "TNFRSF14 is a mediator of atherosclerosis by inducing inflammation." (PMID 35159232, 2022).
cervical carcinoma (3 papers, 2020 to 2024). A carcinoma arising from either the exocervical squamous epithelium or the endocervical glandular epithelium. "We observed that CD274, CEACAM1, LGALS9, PVR and TNFRSF14 were significantly different (P < 0.05) between two groups, providing a novel insight into immunotherapy for cervical carcinoma patients." (PMID 34789197, 2021).
clear cell renal cell carcinoma (3 papers, 2021 to 2025). "Overexpression of TNFRSF14 was associated with poor overall survival and disease-free survival in patients with clear cell renal cell carcinoma, and TNFRSF14 silencing resulted in an evident decline in cell growth both in vitro and in vivo." (PMID 34380460, 2021). "A high level of TNFRSF14 expression was associated with poor overall survival (OS) and disease-free survival (DFS) in patients with clear cell renal cell carcinoma (ccRCC)." (PMID 35057760, 2022).
COVID-19 (3 papers, 2021 to 2025). A disease caused by infection with severe acute respiratory syndrome coronavirus 2. "CD27, TNFRSF14, TNFRS18, and TNFRSF4 were highly expressed in the HLA_DR+ Tregs from severe COVID-19 patients." (PMID 40114921, 2025).
influenza (3 papers, 2018 to 2026). An acute viral infection of the respiratory tract, occurring in isolated cases, in epidemics, or in pandemics; it is caused by serologically different strains of viruses (influenzaviruses) designated A, B, and C, has a 3-day incubation period, and usually lasts for 3 to 10 days. "TNFRSF14 deficiency did not affect AM numbers, but LTβR deficiency prevented AM loss during influenza infection." (PMID 41542776, 2026). "During influenza infection, most of the apoptotic AMs stained positive for TNFRSF14 and/or LTβR." (PMID 41542776, 2026).
MALT lymphoma (3 papers, 2021 to 2023). An indolent, extranodal type of non-Hodgkin lymphoma composed of small B-lymphocytes (centrocyte-like cells). "Among MALT lymphoma of various sites, the most prominent findings were frequent CD274 (52.6%), TNFRSF14 (52.6%), TET2 (85.5%) and TNFAIP3 (30%) mutations in the thyroid cases." (PMID 34021249, 2021). "By targeted sequencing of this gene panel in MALT lymphoma of various sites, we have identified highly frequent inactivating mutations of both CD274 (PD-L1) and TNFRSF14 in thyroid MALT lymphoma." (PMID 34021249, 2021).
non-small cell lung carcinoma (3 papers, 2021 to 2025). A group of at least three distinct histological types of lung cancer, including non-small cell squamous cell carcinoma, adenocarcinoma, and large cell carcinoma. "TNFRSF14 was significantly promoted in non-small cell lung cancer patients with N2 lymph node metastasis or more advanced stage." (PMID 34380460, 2021).
Obesity (3 papers, 2012 to 2022). Accumulation of substantial excess body fat. "Conversely, the other TNFRSF gene members (e.g., TNFRSF4, TNFRSF9, TNFRSF14) were observed to be positively correlated with obesity in mammalian species." (PMID 35053107, 2022).
endometrial carcinoma (2 papers, 2021 to 2023). A malignant tumor arising from the epithelium that lines the cavity of the uterine body. "Therefore, TNFRSF14 is a potential prognostic biomarker for endometrial cancer subtypes." (PMID 34158412, 2021).
esophageal cancer (2 papers, 2024 to 2025). A primary or metastatic malignant neoplasm involving the esophagus. "Silencing TNFRSF14 in esophageal cancer cells inhibits proliferation in vitro, indicating a direct role for tumor‐expressing HVEM in promoting proliferation." (PMID 40105652, 2025).
Hashimoto thyroiditis (2 papers, 2021 to 2025). An autoimmune disorder caused by the production of autoantibodies against thyroid tissue. "Both CD274 and TNFRSF14 genetic changes were significantly associated with Hashimoto’s thyroiditis (p = 0.01, p = 0.04, respectively), and CD274 mutation/deletion additionally associated with increased erythrocyte sedimentation rate (p = 0.0001)." (PMID 34021249, 2021). "Similarly, TNFRSF14 mutation was significantly associated with Hashimoto’s thyroiditis." (PMID 34021249, 2021).
lung fibrosis (2 papers, 2018 to 2021). "Proteins‐H were biologically interesting: TNFRSF14 reported to control TSLP drives pulmonary fibrosis." (PMID 34962717, 2021).
sarcoma (2 papers, 2023 to 2024). A usually aggressive malignant neoplasm of the soft tissue or bone. "Further studies are needed to elucidate the precise molecular mechanisms underlying the interaction between SQLE, C10orf54, and TNFRSF14 in sarcoma." (PMID 38335381, 2024).
squamous carcinoma (2 papers, 2021 to 2025). "Subgroup analysis revealed a similar positive correlation between the gene expression of NR1H4 and TNFRSF14 either in 510 adenocarcinoma or in 484 squamous cell carcinoma samples." (PMID 40985894, 2025). "DDR-deficient types had lower expressions of STING1 (p = 0.01), CD28 (p = 0.020), HLA-DRB6 (p = 0.014) in adenocarcinoma, lower TNFRSF4 (p = 0.017), and TGFB1 expressions (p = 0.033) in squamous carcinoma, and higher CD40 (p = 0.012) and TNFRSF14 expressions (p = 0.022) in SCLC." (PMID 34604048, 2021).
Stroke (2 papers, 2024). Sudden impairment of blood flow to a part of the brain due to occlusion or rupture of an artery to the brain. "We observed 2 proteins (CCL27 and TNFRSF14) associated with subsequent stroke events that have a role in inflammation." (PMID 39038097, 2024).
thymoma (2 papers, 2022 to 2023). A neoplasm arising from the epithelial cells of the thymus. "In CESC, ESCA, GBM, LUSC, and thymoma (THYM), RRM2 had a negative correlation with marker genes of immune activating genes, such as VSTR, TNFSF14, TNFRSF14, and STING1." (PMID 36518297, 2022).